IL33 (interleukin 33)
Diseases named in the same sentence as IL33 in open-access papers (continued):
Sharing a sentence is not in itself a finding about the gene and the disease.
periodontal disease (11 papers, 2014 to 2024). "Experiments with IL-33-receptor-deficient mice showed that IL-33 exacerbates periodontal disease through the induction of RANKL." (PMID 36983201, 2023). "Few works studied the role of IL-33 in periodontal disease, but we hypothesize a possible role of IL-33 in periodontal disease and bone loss." (PMID 24692848, 2014). "Since IL-1 induces IL-33, it is pertinent to think that, by blocking IL-1 with IL-37, there would be an inhibition of inflammation in periodontal diseases; however, these data will need to be confirmed in the future." (PMID 36362030, 2022). "IL-33 also increases in bronchial epithelial cells and periodontal disease upon stimulation with microorganisms or other compounds that can cause inflammation." (PMID 36362030, 2022). "The knowledge of the role of IL-33 in periodontal diseases is relatively scarce, and the results are contradictory." (PMID 31011287, 2019). "IL-33 most likely has three roles in relation to periodontal disease: as an alarmin, a chemoattractant, and a systemic cytokine." (PMID 24692848, 2014). "IL-33 exacerbates periodontal disease, increases IL-6 expression, and enhances a Th17 response." (PMID 28320468, 2017). "The roles of IL-33 derived from gingival epithelial cells, which could include the modulation of innate immune function, need to be defined by further studies and the implications for the pathogenesis of periodontal diseases need to be assessed." (PMID 27058037, 2016). "However, whether IL-33 is induced in gingival epithelial cells during the development of periodontal disease remains unclear." (PMID 27058037, 2016). "In support, inflammatory cytokines IL-6, IL-17A, and IL-33 were increased in the saliva of SLE/periodontal disease patients compared to non-SLE subjects with periodontal disease." (PMID 34950607, 2021). "Salivary levels of IL-6 and IL-33, which regulate cell recruitment amid the transition from acute to chronic inflammation, have been observed to increase in patients contending with obstructive sleep apnea, independent of the severity of their periodontal disease." (PMID 38093226, 2023). "One work would involve studying the osteoclastogenic potential of circulating monocytes in periodontal disease patients in the presence of TNF-α and RANKL with or without IL-33." (PMID 24692848, 2014).
skin cancer (11 papers, 2017 to 2025). "IL-33 is implicated in the onset and progression of skin cancer through its promotion of chronic inflammation, enhancement of tumor cell survival and proliferation, and modulation of the immune response." (PMID 39839625, 2024). "We previously demonstrated that MCPIP1 affects skin cancer progression by regulating the expression of inflammatory molecules such as IL-6, IL-33 and TGF-β." (PMID 39428471, 2024). "Understanding the complex mechanisms by which IL-33 contributes to skin cancer can facilitate the development of novel therapeutic strategies against UV-induced cutaneous carcinogenesis." (PMID 39839625, 2024). "Histological evaluation of the skin tumours showed that 50% of the anti-IL-33-treated mice exhibited mild hyperplasia (grade I), while only 25% were classified as SCC in situ." (PMID 38662248, 2024). "Early studies on the role of IL-33 in skin cancer concluded that inflammatory doses of UVB significantly induced IL-33 expression within the epidermal and dermal layers of both mice and humans." (PMID 30205617, 2018). "Furthermore, the IL-1 family member IL-33 expressed by tumor cells supports skin cancer development in mice via an IL-33/TGF-β feedforward loop." (PMID 36293159, 2022). "A recent study reported that the IL-33/Treg axis could also play a pivotal role in skin cancer progress in other cancer-prone inflammatory diseases of the skin." (PMID 31736655, 2019). "By comparing the effects of IL-33 deficiency (or exogenous administration) on orthotopic PDAC and heterotopic skin tumor growth, the authors demonstrated that TILC2 have tissue-specific effects on PDAC immunity that depended on IL-33/ST2." (PMID 33329534, 2020). "Our results identify and validate the role of IL-33 as an important early danger signal generated in response to inflammatory UVA and UVB radiation that is presumably regulated by inflammasomes which may have consequences for skin cancer growth." (PMID 39839625, 2024).
ankylosing spondylitis (10 papers, 2013 to 2025). An autoimmune chronic inflammatory disorder characterized by inflammation in the vertebral joints of the spine and sacroiliac joints. "Similarity to our results, rs10975519 SNP of the IL-33 gene was associated with the development of ankylosing spondylitis (AS), and the TTCG haplotype formed by s10118795, rs1929992, rs10975519, and rs1048274 indicated a decreased risk of AS." (PMID 34950738, 2021). "We recently showed that development of SpA in SKG mice is associated with increased IL-33 production in the inflamed paws and small intestine, and others have found IL-33 is increased in the serum of patients with ankylosing spondylitis, the most common form of SpA in people." (PMID 32520308, 2020).
atopic asthma (10 papers, 2010 to 2024). An asthma that is characterized by symptoms that are triggered by an allergic reaction caused by inhaled allergens such as dust mite allergen, pet dander, pollen and mold. "Regarding IL-33 rs1888909 polymorphism, a significant association with susceptibility to atopic asthma was revealed in the dominant model (p = 0.036, RR = 0.54, 95%CI 0.53 ÷ 1.08)." (PMID 38731070, 2024). "IL1RL1, also known as ST2 which binds to IL-33, is associated with T2 inflammatory pathways and are upregulated in atopic asthma." (PMID 36076228, 2022). "Large-scale genome-wide association studies have identified minor “G” allele of the single-nucleotide polymorphism rs928413, located in the IL33 promoter area, as a susceptible variant for early childhood and atopic asthma development." (PMID 30257479, 2018). "High constitutive IL33 expression in the Th2high BN is consistent with the heightened susceptibility of this strain to the development of experimental atopic asthma." (PMID 30150981, 2018). "One of them, rs928413 (A/G), is located in the 5′ upstream region of IL33 gene, and its minor “G” allele was identified as a susceptible variant for early childhood asthma and atopic asthma development." (PMID 30257479, 2018). "Moreover, in the case of IL-33 rs992969 in the dominant and codominant models, a significantly lower frequency of [G] allele was observed in patients with atopic asthma and atopy compared with wild-type homozygotes." (PMID 38731070, 2024). "Patients with non-atopic asthma were characterized by a statistically significantly lower concentration of IL-33 compared to the group of patients with atopic asthma (p = 0.04) and the control group (p = 0.01)." (PMID 38731070, 2024). "In atopic asthma, allergens release proteases, which disrupt the epithelial barrier and induce secretion of alarmins such as interleukin-25 (IL-25), interleukin-33 (IL-33), and thymic stromal lymphopoietin (TSLP) from epithelial cells." (PMID 38352244, 2023). "Another example of the significant role of IL-33 in allergic/asthmatic reactions is that IL-33 was overexpressed in skin cells of patients with atopic asthma, and degradation of IgE-primed skin mast cells was mediated by IL-33." (PMID 23209480, 2012). "A similar trend was observed for IL-33 rs1888909 in patients with atopic asthma." (PMID 38731070, 2024). "However, in the results not meeting conventional correction for multiple testing, IL33 SNP rs1342326G (25.7 kb from gene transcription start site (TSS)) showed a level of association with atopic asthma defined by positive skin prick test and clinical diagnosis (p = 0.0097)." (PMID 24066901, 2013).
cerebral infarction (10 papers, 2012 to 2025). An ischemic condition of the brain, producing a persistent focal neurological deficit in the area of distribution of the cerebral arteries. "In the tMCAO model, an ST2 deficiency in mice exacerbated brain infarction and neurological deficits; intracerebroventricular infusions of IL‐33 attenuated brain infarction." (PMID 37464832, 2023). "Using a mouse cerebral infarction model, we showed that brain Tregs are activated and proliferate in both cervical lymph nodes and in the brain through the action of IL-2, IL-33, and serotonin." (PMID 35911740, 2022). "ST2 deficiency in mice exacerbates brain infarction and neurological deficits, and intracerebroventricular infusions of IL‐33 attenuate brain infarction in the tMCAO model." (PMID 32064759, 2020). "We observed that treatment with IL-33 at a dose of 0.2 μg/dose/day for 3 days significantly reduced brain infarct sizes 7 days after HI." (PMID 32859229, 2020). "Exogenous delivery of IL-33 significantly alleviated brain injury 7 days after HI, whereas ST2 deficiency exacerbated brain infarction and neurological deficits post HI." (PMID 32859229, 2020). "In the present study, we found that exogenous delivery of IL-33 significantly ameliorated HI-mediated neonatal brain damage, whereas genetic deficiency of ST2 exacerbated brain infarction and behavioral disorders." (PMID 32859229, 2020). "We found that systemic delivery of IL-33 remarkably alleviated HI-mediated cerebral damage, whereas loss of ST2 aggravated brain infarction and neurological deficits." (PMID 32859229, 2020). "We found that the level of serum IL-33 was significantly higher (P < 0.05) in the small cerebral infarction volume patients group, compared with the large cerebral infarction volume patients group." (PMID 27699084, 2016). "It was suggested that the circulating IL-33 is associated with AIS and may be involved in the regulation of inflammatory reaction in cerebral infarction." (PMID 27699084, 2016). "A recent study also documented that the CNS protection provided by IL-33 is primarily due to its ability to induce IL-10 production in microglia, whereas genetic deletion of ST2 expanded cerebral infarction by switching microglia toward an M1-like phenotype." (PMID 35269441, 2022). "Some of the genes were only regulated at one or the other time-point; an example is IL-33, which was significantly altered at 24 h after cerebral infarct in the PI area, but not at 3 d." (PMID 23284893, 2012). "However, the concentrations of IL‐33 had no statistical correlation with cerebral infarction volume (58.73 ± 21.08 ng/ml vs. 58.86 ± 19.19 ng/ml, p > .05)." (PMID 31397082, 2019).
cholangiocarcinoma (10 papers, 2016 to 2025). A carcinoma that arises from the intrahepatic biliary tree (intrahepatic cholangiocarcinoma) or from the junction, or adjacent to the junction, of the right and left hepatic ducts (hilar cholangiocarcinoma). "In line with the altered cytokine profile, increased IL-33, known as a chromatin-associated cytokine known to influence epigenetics, has been correlated with the development of several types of cancer, including progression to cholangiocarcinoma." (PMID 40476597, 2025). "In cholangiocarcinoma, high-dose IL-33 inhibits cell migration, while low-dose IL-33 promotes cell migration." (PMID 38825642, 2024). "It has been reported that intracellular and extracellular IL-33 play distinct mechanistic roles; intracellular IL-33 attenuates extracellular IL-33-induced cholangiocarcinoma cell proliferation and invasion via NF-κB and GSK-3β pathways." (PMID 36291105, 2022). "One study investigating the link between IL33 and the development of cholangiocarcinoma found that daily injections of IL33 increased the size and thickness of extrahepatic bile ducts and induced metaplastic changes." (PMID 34235145, 2021). "Interleukin 33 (IL-33) promotes cholangiocarcinoma (CCA) genesis in a mouse model, however, its function in human CCA has not been clearly understood." (PMID 33046978, 2020). "Induction of the IL-33/ILC2/IL-13 circuit promoted epithelial repair, however, induction of this circuit in mice with constitutively activated oncogenic AKT and YAP in bile ducts induced cholangiocarcinoma with liver metastases." (PMID 30205617, 2018).
chronic heart failure (10 papers, 2008 to 2022). "Patients with chronic heart failure have a reduced IL-33/sST2 ratio, suggesting an importance for IL-33 bioactivity, which is hindered by inhibitory sST2." (PMID 34531552, 2022). "IL1RL1 codes for the receptor of IL-33, an important biomarker of myocardial stress, fibrosis, and chronic heart failure secreted in response to cell damage." (PMID 31924244, 2020). "miR-487b has the ability to improve chronic heart failure by reducing the myocardial apoptosis and inflammatory response through the IL-33/ST2 signaling pathway." (PMID 32178736, 2020). "IL-33 was found recently in endomyocardial biopsies from patients with aortic valve stenosis and congestive heart failure." (PMID 23567618, 2013). "One study has investigated the role of IL-33 expression in rats with chronic heart failure." (PMID 34909658, 2021). "Interestingly, serum IL-33 levels in patients with chronic heart failure are elevated, and it has been proven to have antioxidant effects." (PMID 33854693, 2021). "The IL-33/ST2 signaling axis was inhibited using the microRNA miR487b, which was found to reduce the expression of the IL-33 protein, resulting in improved cardiac morphology and reduced collagen expression in an in vivo model of chronic heart failure induces by coronary artery occlusion." (PMID 34909658, 2021). "Interleukin-33 (IL-33) has been linked to chronic heart failure (CHF) in animal studies, but data on serum IL-33 levels in human CHF are not available." (PMID 22682001, 2012).
esophageal squamous cell carcinoma (10 papers, 2018 to 2025). Esophageal squamous cell carcinoma (ESCC) is a type of esophageal carcinoma (EC) that can affect any part of the esophagus, but is usually located in the upper or middle third. "In esophageal squamous cell carcinoma, a correlation has been observed between increased levels of IL‐33 and increased density of FOXP3+ Tregs, which are thought to enhance immune escape." (PMID 40860436, 2025). "More recent studies have further elaborated on IL-33 as being a transcriptional regulator of nuclear factor NF- κB where it has demonstrated involvement in the pathogenesis of esophageal squamous cell carcinoma and atherosclerosis, as well as in the activation of endothelial cells." (PMID 32363166, 2020). "In esophageal squamous cell carcinoma (ESCC), IL-33 stimulated the production of CCL2 through TGF-β involving Treg cell recruitment." (PMID 34209038, 2021). "The expressions of IL‐33 and indicators related to macrophage polarization in oesophageal squamous cell carcinoma (ESCC) tissues and peripheral blood mononuclear cell (PBMC)–derived macrophages were determined." (PMID 33305406, 2021). "Using immunohistochemistry (IHC) and double immunofluorescence staining, we characterized the cellular and clinicopathological features of the IL-33/ST2 axis in different compartments in human esophageal squamous cell carcinoma (ESCC) surgical specimens." (PMID 30559604, 2018). "IL-33 promoted cancer cell migration and invasion via inducing epithelial-to-mesenchymal transition by the activation of MCP-1 in esophageal squamous cell carcinoma." (PMID 37629196, 2023). "During the occurrence and development of human esophageal squamous cell carcinoma (ESCC), the activation of ODC can increase the secretion of IL-33 in the tumor site, thereby promoting the polarization of macrophages to the anti-inflammatory M2 phenotype." (PMID 36119047, 2022).
Granuloma (10 papers, 2015 to 2024). A compact, organized collection of mature mononuclear phagocytes, which may be but is not necessarily accompanied by accessory features such as necrosis. "Blocking IL-33 signaling by knockout of St2 or Il33 gene is reported to enhance host mortality by modulating granuloma-mediated pathology." (PMID 39559705, 2024). "IL-33 was detected in the nuclei of endothelial cells (mainly in periparasitic tissues) and some hepatocytes (only in close parenchyma), but the density of IL-33+ nuclei was similar between parenchyma and periparasitic granuloma." (PMID 36786637, 2023). "IL-33 was located in cells at the outer rim of granulomas while ST2 was found relatively more in cells inside." (PMID 31200771, 2019). "Granulomas in the skin and lungs have recently been described as a source of nuclear IL-33 expression and its expression was strongly correlated with the presence of systemic disease." (PMID 25866481, 2015). "The data indicated that the local inflammatory milieu within each sarcoidal granuloma is critical for IL-33 expression and that IL-33 expression represents a novel biomarker for systemic involvement of the disease." (PMID 25866481, 2015). "ST2 deficiency or blockade of IL-33 using soluble ST2 treatment or neutralizing antibodies resulted in obvious less Th2 cytokine production and Th2-mediated pathology in livers, including marked decreases in granuloma size and fibrosis extent." (PMID 39559705, 2024). "Conversely, granulomas have been reported to be a source of IL-33 in pulmonary sarcoidosis." (PMID 33050608, 2020). "However, the actual mechanism used by IL-33 to promote the formation of granuloma and fibrosis in the liver during Sj infection needs to be further delineated." (PMID 31200771, 2019). "In a mouse model of schistosomiasis, ST2 deficiency or blockade of IL-33 using soluble ST2 treatment or neutralizing antibodies showed significantly less Th2-mediated pathology, including marked decreases in granuloma and fibrosis formation, or Th2 cytokine production." (PMID 30345011, 2018). "IL-33- and ST2-positive staining cells were mostly located on the outside rim and inside of granulomas, respectively." (PMID 31200771, 2019). "The trends observed in the present study are in the same direction, with the absence of IL-33 not affecting the development of pathology nor the number and size of granulomas in the intestines of IL-33−/− mice at time points beyond the 6 wpi." (PMID 33482904, 2021). "Their study demonstrated the possible involvement of RANKL, TNF-α, IL-33, cathepsin K, and OPG in the development of radicular cysts and periapical granulomas, with emphasis on the highest immunoreactivity of cathepsin in cysts and TNF-α and OPG in granulomas." (PMID 31011287, 2019). "Morphometric analysis of the brown-stained areas in hepatic granulomas of chronically infected mice from both mouse strains confirmed a significantly lower expression of α-SMA+ cells in granulomas formed in the absence of the activation of the IL-33/ST2 pathway." (PMID 37373379, 2023).